SFRP1 (secreted frizzled related protein 1)
Diseases named in the same sentence as SFRP1 in open-access papers (continued):
Sharing a sentence is not in itself a finding about the gene and the disease.
ovarian carcinoma (25 papers, 2007 to 2026). A malignant neoplasm originating from the surface ovarian epithelium. "SFRP1 methylation has also been linked to ovarian cancer recurrence and shorter OS." (PMID 39729237, 2025). "The miR-1180-3p overexpression has been found to enhance cell division and glycolysis in ovarian cancer cells through the SFRP1/Wnt signaling pathway." (PMID 39473825, 2024). "BM-derived MSCs express high levels of miR-1180-3p, which is critical to their induction of cell proliferation and glycolysis in an ovarian cancer model, where miR-1180-3p can modulate Wnt signaling by targeting SFRP1." (PMID 38671809, 2024). "Hsa_circ_0001445 is reduced in ovarian cancer cells, resulting in an elevation of miR‐576‐5p that subsequently decreases SFRP1 expression." (PMID 36259450, 2023). "Methylation of SFRP1 was identified with a frequency of 5–35% in epithelial ovarian cancer and was correlated with survival." (PMID 34778370, 2021). "We also found that up-regulation of miR-1180 activated Wnt signaling by targeting SFRP1 in ovarian cancer cells." (PMID 30936781, 2019). "Our study for the first time verified that miR-1180 functioned as an onco-miRNA in ovarian cancer cell by targeting SFRP1 expression in ovarian cancer cells." (PMID 30936781, 2019). "The relationship between miR-1180 and SFRP1 showed that miR-1180 expression was negatively related to SFRP1 mRNA levels in ovarian cancer tissues." (PMID 30936781, 2019). "We also found that up-regulation of miR-1180 decreased SFRP1 expression, which activated Wnt signaling in ovarian cancer cells." (PMID 30936781, 2019). "In summary, we found that elevated expression of miR-1207 promoted stem cell-like traits and tumorigenicity in ovarian cancer by simultaneously suppressing multiple inhibitors of Wnt/β-catenin signaling, namely SFRP1, AXIN2, and ICAT." (PMID 26337084, 2015). "We previously performed transcription profiling in ovarian cancer specimens compared to normal ovarian controls which revealed aberrant expression of SFRP1 and SFRP4 in ovarian cancers." (PMID 22363760, 2012). "In ovarian cancer, SFRP1 was the first family member reported to be hypermethylated and silenced in ovarian cancer cell lines and patient specimens but not in normal controls, suggesting a potential role as a tumor suppressor." (PMID 22363760, 2012). "Taken together, this study establishes the first potential evidence that EZH2 inhibition may reprogram eccDNA dynamics to potentially restore SFRP1 tumor suppressor expression in ovarian cancer." (PMID 41744650, 2026). "The result indicated that miR-1180 could activate Wnt signal pathways because Wnt5a, β-catenin, myc and cyclinD1 levels increased in ovarian cancer cells with miR-1180 and SFRP1 overexpression." (PMID 30936781, 2019). "To determine whether ARID3BFL overexpression regulates these genes in other ovarian cancer cell lines, we performed qRT-PCR for SFRP1 and WISP1 on OVCA429 cells transduced with RFP or ARID3B." (PMID 25327563, 2014). "DO analysis revealed that DEGs PSAT1, FOLR1, ABCB1, SFRP1, SFRP1, BUB1B have a greater association with female reproductive system tumor-related diseases, such as malignant ovarian surface epithelial-mesenchymal tumor, ovarian epithelial carcinoma, and ovarian cancer." (PMID 35719392, 2022). "The correlation between high SFRP1 expression with patients’ survival was diverse and was correlated with poor prognoses in bladder carcinoma, kidney renal papillary cell carcinoma, lung squamous cell carcinoma, ovarian cancer, and rectal and stomach adenocarcinoma." (PMID 32764696, 2020). "Herein, the promoter methylation of seven ovarian cancer-specific genes (RASSF1A, DAPK1, SOX1, HOXA9, HIC1, SPARC, and SFRP1) was analyzed quantitatively in 120 tissue samples by MethyLight assay." (PMID 34778370, 2021).
ovarian carcinoma (continued). "Examination of the resulting network shows that RPS19, PNOC, SFRP1 and KCNJ16 are connected to other frequently altered genes, including MYC or EIF3E as oncogenes, from TCGA ovarian cancer dataset." (PMID 30255801, 2018). "SFRP1 SFRP2 and SFRP5 are methylated in ovarian cancer, and experimental overexpression or knockdown, demonstrated that epigenetic silencing of SFRP5 was related to tumour growth, invasion (via EMT) and chemosensitivity in ovarian cancer." (PMID 27196929, 2016). "Our current study found that SFRP1, AXIN2, and ICAT were targeted and suppressed by miR-1207 in ovarian cancer, which promoted stem cell-like traits through highly activation of Wnt/β-catenin signaling." (PMID 26337084, 2015). "In addition, our findings showed that the methylation levels of candidate genes (HIC1, HOXA9, SOX1, DAPK1, RASSF1A, SFRP1, and SPARC) were significantly elevated in patients with ovarian cancer and was highly cancer-specific, which is in concord with the previously published reports." (PMID 34778370, 2021). "Furthermore, we demonstrated that miR-1207 enhanced ovarian cancer stem-like traits through directly targeting SFRP1, AXIN2 and ICAT, which are vital negative modulators of the Wnt/β-catenin pathway." (PMID 26337084, 2015). "In the current study, we found that miR-1207 was significantly overexpressed in ovarian cancer and enhanced the stem cell-like traits of ovarian cancer cells by downregulating of multiple negative modulators of the Wnt/β-catenin pathway, including SFRP1, AXIN2 and ICAT." (PMID 26337084, 2015). "However, there was no relevant expression of SFRP1 and BUB1B genes detected in the validation set B. Due to the high lethality of ovarian cancer, we took the potential genes obtained from validation set A and validation set B. Thus, altogether, 9 diagnostic genes were obtained." (PMID 35719392, 2022).
glioma (23 papers, 2016 to 2025). A benign or malignant brain and spinal cord tumor that arises from glial cells (astrocytes, oligodendrocytes, ependymal cells). "SFRP1 has been identified as a tumour suppressor gene in glioma, silenced by aberrant promoter methylation and loss of function mutations." (PMID 40418209, 2025). "SFRP1 also impairs the malignant growth of glioma in vitro, which is indicated to be potentially linked to the blockade of the Wnt/β‐catenin pathway." (PMID 36756719, 2023). "SFRP1 encodes a WNT inhibitor the expression of which has been shown to be of positive prognostic relevance in gliomas." (PMID 27556305, 2016). "In addition, Sohlh1 was positively correlated with the expression of SFRP1, whereas negatively associated with the expression of Nestin in glioma tissues, suggesting a tumour suppressive role in the stemness of glioma." (PMID 40418209, 2025). "Therefore, we also verified the association of this pathway with SFRP1 expression in U87 and U251 glioma cells." (PMID 36756719, 2023). "MiR-27a down-regulates Sfrp1 and induces Wnt/β-catenin signalling, causing glioma." (PMID 32484208, 2020). "Clinically, we observed a significant inverse correlation between Sohlh1 and Nestin expression levels, and a positive correlation between Sohlh1 and SFRP1 expression in glioma tissues." (PMID 40418209, 2025). "Taken together, our findings suggested that the Sohlh1/SFRP1/Wnt/β‐catenin signalling pathway represented one of the key molecular networks involved in the regulation of GSLC biology in glioma." (PMID 40418209, 2025). "Our results supplied additional evidence that miR‐542‐3p‐induced inhibition of SFRP1 and resultant SFRP1‐dependent blockade of the Wnt/β‐catenin pathway underpinned the tumor‐inhibitory effect of lncMEG3 elevation in glioma following MTE treatment." (PMID 36756719, 2023). "U87 and U251 glioma cells upon pcDNA3.1‐SFRP1 treatment was found to have elevated SFRP1 and E‐cadherin expression and reduced p‐GSK‐3β, β‐catenin, N‐cadherin, Vimentin, and Snail expression, with no change in GSK‐3β expression." (PMID 36756719, 2023). "For instance, elevated SFRP1 protein levels in glioma patients are linked to prolonged overall survival; downregulation of SFRP1 and activation of Wnt may give rise to the development of infiltrative glioma phenotype during the early phrases of glioma progression." (PMID 36756719, 2023). "To conclude, restoration of SFRP1 can restrict the malignant phenotype of glioma cells by restraining the activation of the Wnt/β‐catenin pathway." (PMID 36756719, 2023). "Lastly, SFRP1 was unveiled to block the Wnt/β‐catenin pathway, whereby limiting the malignant behaviors of glioma cells." (PMID 36756719, 2023). "Marsdenia tenacissima extract increases lncMEG3 expression to regulate miR‐542‐3p/SFRP1 and inhibit Wnt/β‐catenin signaling pathway, thereby suppressing glioma cell proliferation, migration, and invasion." (PMID 36756719, 2023). "Recombinant SFRP1 acts as an inhibitor of nuclear β‐catenin in glioma stem cells, halting their proliferation and inducing apoptosis." (PMID 36756719, 2023). "Previously, we and others found that Wnt/β-catenin signaling is hyperactivated in glioma cells due to promoter methylation of its antagonists, including SFRP1 and RUNX3." (PMID 34681943, 2021). "As the impact of NaBu on GBM cells in the context of Wnt signaling pathway was not analyzed so far, this novel finding is of great importance, especially since our previous study revealed that SFRP1 methylation predicts shorter survival of glioma patients." (PMID 34681943, 2021). "SFRP1 is negatively associated with cancer development and progression, and hypermethylation of SFRP1 promoter and transcription suppression has been demonstrated for brain cancers of glial origin, such as glioma and astrocytoma." (PMID 32098349, 2020). "The expressions of FZD7, along with other two genes, SFRP1 and SFRP4, were identified to be associated with poor prognosis in glioma patients." (PMID 29050331, 2017).
glioma (continued). "Based on our data, CBX7 should be added to this growing list of β-catenin regulators in glioma that includes SFRP1, DKK1 and Wif1." (PMID 28388562, 2017). "This suggestion is further supported by recent data on SFRP1 mRNA levels in glioma patients presented in the REMBRANT (Repository of Molecular Brain Neoplasia Data) and TCGA (The Cancer Genome Atlas) databases." (PMID 26337424, 2016). "Sfrp1 and Sfrp2 are produced by long-term and ex vivo malignant glioma cells and are thought to act as survival and proliferation-promoting factors." (PMID 27048460, 2016). "Beside the genes, which were described earlier as possible targets of epigenetic silencing in gliomas (SFRP1, SFRP2, DKK1), the methylation of PPP2R2B, SOX17, and DACH1 was also assessed." (PMID 26337424, 2016). "Dysregulation of the Wnt canonical pathway leading to beta-catenin activation has been detected in glioma patients with overexpression of WNT3a and epigenetic-driven downregulation of inhibitors like SFRP1, Dkk1 or Wif1." (PMID 27613837, 2016). "MTE suppresses glioma via the lncMEG3/miR‐542‐3p/SFRP1/Wnt/β‐catenin axis." (PMID 36756719, 2023). "To confirm this conjecture, we first performed qRT‐PCR for the detection of miR‐542‐3p and SFRP1 expression in NHAs and U87 and U251 glioma cells, and a high expression of miR‐542‐3p and a low expression of SFRP1 were observed in U87 and U251 cells in comparison to NHAs." (PMID 36756719, 2023). "Coincidentally, several studies have additionally revealed the involvement of SFRP1/Wnt in glioma." (PMID 36756719, 2023). "Lastly, we probed whether the MTE‐mediated inhibition of glioma cells worked by suppressing the Wnt/β‐catenin pathway activation and elevating SFRP1 expression via the lncMEG3/miR‐542‐3p axis." (PMID 36756719, 2023). "Based on this, we could speculate that the MTE treatment suppressed the malignant behaviors of glioma cells through upregulating lncMEG3, reducing miR‐542‐3p expression, and finally upregulating SFRP1 expression." (PMID 36756719, 2023). "We next verified whether the MTE‐mediated inhibition of glioma cells was acted by blocking the Wnt/β‐catenin pathway, decreasing miR‐542‐3p expression and elevating SFRP1 expression." (PMID 36756719, 2023). "Additionally, SFRP1 overexpression was witnessed to repress the proliferative, migratory, and invasive functions of glioma cells as well as to block the induced EMT during cancer progression." (PMID 36756719, 2023). "A battery of function experiments, including the CCK‐8 viability test, colony formation assay, scratch migration assay, and Transwell invasion assay, was executed to address the responses of glioma cells to MTE treatment and gain or loss of function of lncMEG3, miR‐542‐3p, and SFRP1." (PMID 36756719, 2023). "Furthermore, SFRP1 exerts an antitumor role in glioma through suppressing the Wnt/β‐catenin pathway." (PMID 36756719, 2023). "Interestingly, we observed a general decrease in promoter DNA methylation of RASSF1A with increasing glioma malignancy (this effect was also observed to a lesser extent for SFRP1, MGMT, and RUNX3)." (PMID 32783304, 2020). "miR-328 suppresses the survival of cancer cells by targeting PLCE1 in esophageal cancer, inhibits epithelial to-mesenchymal transition in renal tubular cells by targeting CD44, and regulates cell invasion and proliferation in glioma cells by targeting SFRP1 and in melanoma cells by targeting TGFb2." (PMID 29374351, 2018). "Moreover, SFRP1 promoter methylation can be regarded as a potential indicator of glioma patients’ survival." (PMID 26337424, 2016). "Moreover, SFRP1 methylation predicts shorter survival of patients with gliomas." (PMID 32783304, 2020). "Moreover, correlation of SFRP1 methylation with tumor grade and patients’ survival may suggest its potential as a prognostic biomarker for glioma patients." (PMID 26337424, 2016). "Moreover, SFRP1 methylation can be regarded as a potential indicator of glioma patient survival." (PMID 26337424, 2016).
glioma (continued). "Collectively, our findings suggest an important role of the Sohlh1/SFRP1/Wnt/β‐catenin pathway in regulating GSLC stemness and differentiation, suggesting potential therapeutic targets for glioma." (PMID 40418209, 2025). "In glioma, experimentation with SFRP1 as an inhibitor of the WNT pathway led to the discovery of its role as a direct target of miR-32, which is highly upregulated in invasive glioma cells." (PMID 34012965, 2021). "Secreted frizzled-related protein 1 (SFRP1) is hypermethylated due to overexpression of miR-328, leading to the activation of Wnt signaling in infiltrative gliomas." (PMID 32906592, 2020). "Forty‐six glioma samples and one non‐neoplastic brain sample were analyzed by MS‐HRM in terms of SFRP1, SFRP2, RUNX3, CBLN4, INA, MGMT, and RASSF1A promoter methylation." (PMID 32783304, 2020). "The methylation of SFRP1, SFRP2, PPP2R2B, DKK1, SOX17, and DACH1 was analyzed in 64 glioma samples using methylation-specific polymerase chain reaction (MSP)." (PMID 26337424, 2016).
pancreatic cancer (22 papers, 2008 to 2025). "SFRP1 is a tumor suppressor gene with decreased levels associated with poor prognostic outcomes in different cancer types including pancreatic cancer." (PMID 37533202, 2023). "Previous gene expression studies of stromal tissue from pancreatic cancer found SFRP1 to be downregulated in pancreatic cancer-associated connective tissue and assumed abundant DNA methylation as a possible mechanism but did not actually investigate SFRP1 promoter methylation." (PMID 36765639, 2023). "A defined block of seven CpG sites within the core CpG island was identified, which confirmed our in silico results by showing significantly higher SFRP1 methylation in pancreatic cancer specimens than in normal pancreatic tissue." (PMID 36765639, 2023). "Our aim of this study was to identify those regions of the SFRP1 promoter DNA sequence as precisely as possible, which are frequently hypermethylated in pancreatic cancer and involved in downregulation of SFRP1 expression." (PMID 36765639, 2023). "In this study, we therefore aimed to identify as precisely as possible the region in the SFRP1 promoter that is frequently hypermethylated in pancreatic cancer tissue." (PMID 36765639, 2023). "By selecting this core CpG island, we were able to determine a median overall survival benefit for the low SFRP1 methylation group compared to the high SFRP1 methylation group (702 versus 517 days, p = 0.01) in the TCGA pancreatic cancer cohort." (PMID 36765639, 2023). "In the pancreatic cancer tissue, we demonstrated a significantly higher SFRP1 promoter DNA methylation in CGI2 than in normal acinar tissue." (PMID 36765639, 2023). "First, we used the TCGA data set to define CpG-rich regions flanking the SFRP1 transcription start site that were significantly more methylated in pancreatic cancer compared to normal pancreatic acinar tissue." (PMID 36765639, 2023). "The SFRP1 promoter region, which we focused on for DNA methylation analysis in pancreatic cancer, has only been analyzed in a study for renal cell cancer." (PMID 36765639, 2023). "We performed Kaplan–Meier analysis in dependence of the overall survival of the pancreatic cancer patients and their SFRP1 methylation status dichotomized by the median in low and high methylation." (PMID 36765639, 2023). "So far, the class 2 tumor suppressor gene SFRP1 has been described as a frequently methylated gene in pancreatic cancer, either directly in cancerous tissue or in blood-based plasma-derived cell-free DNA." (PMID 36765639, 2023). "Promoter hypermethylation of the tumor suppressor gene Secreted frizzled-related protein 1 (SFRP1) seems to be correlated with poor response to gemcitabine treatment in stage IV pancreatic cancer." (PMID 36765639, 2023). "Our study examined the genomic SFRP1 sequence and its potential regions for de novo DNA methylation in pancreatic cancer with key effects on SFRP1 expression silencing." (PMID 36765639, 2023). "First, we have analyzed in cfDNA from eight mPDAC patients the methylation levels of five genes BMP3, NPTX2, SPARC, TFPI2 and SFRP1 known to be aberrantly methylated in pancreatic cancer." (PMID 37481552, 2023). "We propose a compact pyrosequencing assay that can be used in the future to further investigate the prognostic value of SFRP1 promoter hypermethylation in predicting pancreatic cancer chemoresistance." (PMID 36765639, 2023). "The mRNA expression levels of SFRP2 and SFRP4 were significantly elevated in the breast, gastric, and pancreatic cancer tissues, while SFRP1 showed significantly decreased expression in datasets from 15 different types of cancer." (PMID 34205081, 2021). "The promoter region of SFRP1 is often methylated in cfDNA from pancreatic cancer patients, so we also focused on this region." (PMID 32520974, 2020). "Another study has also demonstrated thathigh expression of miR-940 promotes proliferation of pancreatic cancer throughregulating GSK3β and sFRP1." (PMID 31085718, 2019).